NEK2 (NIMA related kinase 2)
Diseases named in the same sentence as NEK2 in open-access papers (continued):
Sharing a sentence is not in itself a finding about the gene and the disease.
endometriosis (2 papers, 2024 to 2025). The growth of functional endometrial tissue in anatomic sites outside the uterine body. "Taken together, these findings indicate that NEK2 regulates the development of endometriosis and associated disorders of decidualization through the phosphorylation of FOXO1, providing a new therapeutic target for its treatment." (PMID 38795132, 2024). "Our study lays a theoretical foundation for developing new strategies for the treatment of endometriosis and its associated endometrial decidualization defects by targeting NEK2 and FOXO1." (PMID 38795132, 2024). "Our study has identified eight potential mitosis hub genes (KIF4A, BUB1B, NEK2, FBXO5, KIF11, CENPE, CCNA2, and NCAPG) that exhibit excellent diagnostic properties for endometriosis." (PMID 40772274, 2025). "To measure the levels of endogenous FOXO1 protein, we overexpressed or knocked down NEK2 in endometriosis cells." (PMID 38795132, 2024). "We find that NEK2 expression is increased in the ectopic and eutopic endometrium of patients with endometriosis." (PMID 38795132, 2024). "IHC revealed significantly elevated levels of NEK2 expression in the ectopic endometrium of patients with endometriosis compared with controls." (PMID 38795132, 2024). "This study revealed the increase of NEK2 in endometriosis compared to controls, and NEK2 was negatively correlated with FOXO1." (PMID 38795132, 2024). "NEK2 promoted the proliferation, migration, and invasion of endometriotic cells and impaired the decidualization of endometriosis eutopic endometrial stromal cells by phosphorylating FOXO1 at Ser184 and reducing its stability." (PMID 38795132, 2024). "Western blot data further confirmed the increased levels of NEK2 in the ectopic endometrium of patients with endometriosis." (PMID 38795132, 2024). "In our study, immunohistochemical results showed that NEK2 expression was significantly increased in the secretory phase eutopic endometrium of endometriosis than in the normal secretory phase endometrium." (PMID 38795132, 2024). "In this study, we used C57BL/6 female mice to establish endometriosis models to determine how NEK2 affects the growth of endometriosis in vivo." (PMID 38795132, 2024). "Then, we identified 11 potential mitosis-related downregulated hub genes, among which eight genes (KIF4A, BUB1B, NEK2, FBXO5, KIF11, CENPE, CCNA2, and NCAPG) showed good diagnostic properties of endometriosis and two genes (CCNA2, CENPE) were closely related to infertile endometriosis." (PMID 40772274, 2025). "In summary, NEK2 promotes the progression of endometriosis both in vitro and in vivo." (PMID 38795132, 2024). "The NEK2 protein levels were found to be significantly increased in endometriosis." (PMID 38795132, 2024). "Furthermore, INH1, an inhibitor of NEK2, inhibits the growth of ectopic lesions in mouse models of endometriosis and promotes endometrial decidualization in mouse models of artificially induced decidualization." (PMID 38795132, 2024). "Therefore, this study aims to investigate the effects of NEK2 overexpression or knockdown on the proliferation, migration, invasion and decidualization of endometrial cells in endometriosis." (PMID 38795132, 2024). "In addition, we investigated the role of NEK2 in endometriosis by altering NEK2 expression in endometriosis cells." (PMID 38795132, 2024). "To determine whether NEK2 is involved in the development of endometriosis, we overexpressed and knocked down NEK2 in EESC and 11Z cells, respectively." (PMID 38795132, 2024). "To verify whether NEK2 damages decidualization of endometrial stromal cells in vivo, we first established a mouse model of endometriosis." (PMID 38795132, 2024). "We investigate whether the NEK2 inhibitor INH1 has therapeutic effects in endometriosis mouse model and artificially induced decidualization mouse model." (PMID 38795132, 2024).
endometriosis (continued). "However, the role of NEK2 in endometriosis and whether it affects the decidualization of the eutopic endometrium in endometriosis have not been investigated." (PMID 38795132, 2024). "We used the GSE25628 dataset to detect the expression of selected target genes, and the results showed that the differential expression of eight MRHGs (KIF4A, BUB1B, NEK2, FBXO5, KIF11, CENPE, CCNA2, and NCAPG) between control and endometriosis patients was consistent with predictions." (PMID 40772274, 2025). "Our findings demonstrated that NEK2 and FOXO1 were negatively correlated in endometriosis." (PMID 38795132, 2024). "In addition, NEK2 inhibitor INH1 inhibited cell proliferation, migration, invasion and suppressed the growth of endometriosis lesions in mouse models of endometriosis." (PMID 38795132, 2024). "The evidence from cellular experiments suggests that NEK2 directly interacts with FOXO1 and phosphorylates at the Ser184 site inhibits the protein stability of FOXO1, thereby enhancing proliferation, migration, invasion and impairing decidualization of stromal cells in endometriosis." (PMID 38795132, 2024).
Ewing sarcoma (2 papers, 2015 to 2021). A small round cell tumor that lacks morphologic, immunohistochemical, and electron microscopic evidence of neuroectodermal differentiation. "In 2002, Wai used oligonucleotide chips to analyze solid tumor cell lines in children and found that NEK2 was overexpressed in Ewing's sarcoma in children, suggesting for the first time that abnormal expression of NEK2 was correlated with the occurrence and development of tumors." (PMID 34706700, 2021).
gallbladder cancer (2 papers, 2024 to 2025). "Most interestingly three genes TRIP13, NEK2, and TPX2 were identified as key players linked to the development and progression of gallbladder cancer." (PMID 38914609, 2024). "This study, using a network-centric approach, reveals the complex interaction among differentially expressed genes (DEGs) in gallbladder cancer (GBC), highlighting the crucial roles of TRIP13, NEK2, and TPX2 in steering the disease's development and prognosis." (PMID 38914609, 2024).
Hepatitis C (2 papers, 2012 to 2021). "NEK2 expression levels were significantly elevated in fibrotic tissue of Hepatitis C patients compared to both normal controls (p = 0.002) and HCC (p<0.001)." (PMID 22539975, 2012).
Metastatic Cancers (2 papers, 2022). A carcinoma which has spread from the original site of growth to another anatomic site. "Moreover, NEK2 was overexpressed in metastatic cancers as well, including lymph node and liver metastases." (PMID 35031599, 2022).
non-Hodgkin lymphoma (2 papers, 2020 to 2026). Distinct from Hodgkin lymphoma both morphologically and biologically, non-Hodgkin lymphoma (NHL) is characterized by the absence of Reed-Sternberg cells, can occur at any age, and usually presents as a localized or generalized lymphadenopathy associated with fever and weight loss. "NEK2 is a cell cycle-regulated kinase that coordinates cell division at multiple levels and is associated with disease progression in non-Hodgkin lymphomas." (PMID 33391157, 2020). "This c.3227C>T (p.Ser1076Leu) substitution is predicted to affect the modification of the Ser1076 residue by the cell cycle-regulated kinase NEK2, which coordinates cell division at multiple levels and is associated with disease progression in non-Hodgkin lymphomas." (PMID 33391157, 2020).
pituitary tumor (2 papers, 2021 to 2025). A benign or malignant neoplasm affecting the pituitary gland. "NEK2 was upregulated in PAs and inhibition of NEK2 impaired the proliferation of pituitary tumor cell lines in vitro and in vivo." (PMID 33754007, 2021). "Herein, we demonstrated that NEK2 promoted pituitary tumor cell growth in vivo and in vitro, and that it affected DA sensitivity." (PMID 33754007, 2021). "NEK2 overexpression significantly promoted pituitary tumor GH3 and MMQ cell proliferation, and it impaired cellular sensitivity to CAB." (PMID 33754007, 2021). "To investigate the role of NEK2 in prolactinomas, we stably overexpressed and knocked down NEK2 by lentiviral mediation in pituitary tumor GH3 and MMQ cells, and executed cell viability and proliferation assays." (PMID 33754007, 2021). "Collectively, these data suggested that NEK2 is a specific substrate of USP7 in pituitary tumor cells." (PMID 33754007, 2021). "Moreover, a recent study demonstrated that NEK2, whose overexpression significantly promotes pituitary tumor growth and cell proliferation, is upregulated in resistant prolactinomas, thereby impairing cellular sensitivity to cabergoline." (PMID 40995599, 2025). "Moreover, NEK2 knockdown sensitized pituitary tumor cell lines to CAB, increasing its anti-proliferative actions by inactivating the Wnt-signaling pathway." (PMID 33754007, 2021). "We posit that targeting USP7 or NEK2 might have therapeutic potential in pituitary tumors, especially dopamine-resistant tumors marked by high NEK2 expression." (PMID 33754007, 2021). "In the present study we furthermore found that NEK2 expression was inhibited by CAB in a dose- and time-dependent manner, and that silencing of NEK2 sensitized pituitary tumor cells to CAB." (PMID 33754007, 2021).
renal cell carcinoma (2 papers, 2022 to 2023). "NEK2 and NUF2 have also well established roles in cell cycle regulation and cell proliferation and their overexpression was associated with a variety of cancer types including renal cell carcinoma." (PMID 35954157, 2022).
adenoma (1 paper, 2014). A neoplasm arising from the epithelium. "When we analyzed these data, we observed that NEK2 is overexpressed in carcinomas compared to adenomas and normal adrenals." (PMID 25279464, 2014).
aneuploidy (1 paper, 2022). Chromosomal disorder consisting of the presence a chromosomal abnormality in which there is an addition or loss of chromosomes within a set. "The overexpression of Nek2 and TTK also correlates with the higher aneuploidy indexes in NHB women." (PMID 36494865, 2022).
B cell lymphomas (1 paper, 2014). "Elevated expression of Nek2 is a common phenomenon in B cell lymphomas and other neoplastic diseases." (PMID 25485281, 2014).
B-cell neoplasm (1 paper, 2014). A group of heterogeneous lymphoid tumors generally expressing one or more B-cell antigens or representing malignant transformations of B-lymphocytes. "Nek2 is frequently overexpressed and associated with disease progression in many types of cancer including B cell neoplasm." (PMID 25485281, 2014).
bile duct cancer (1 paper, 2012). "Up-regulated expression of IGF2BP3, NEK2 and HOXB7 mRNA in our study confirms recent reports suggesting detection of tumor-associated gene expression profiles in biliary tract specimens as potentially useful tools in the diagnosis of bile duct cancer." (PMID 22879911, 2012).
ductal carcinoma in situ (1 paper, 2020). "Overexpression of NEK2 was detected in ductal carcinoma in situ (DCIS) tumors, invasive ductal carcinoma, and invasive lobular carcinoma." (PMID 32294979, 2020).
esophageal adenocarcinoma (1 paper, 2025). A malignant tumor with glandular differentiation arising predominantly from Barrett mucosa in the lower third of the esophagus. "Among these genes, NEK2 is the most frequently upregulated NEK in esophageal adenocarcinoma at both the mRNA and protein levels." (PMID 40076620, 2025). "We have reported that the gene expression levels of NEK2, NEK3, and NEK6 are frequently upregulated in esophageal adenocarcinoma as compared to normal esophageal epithelium." (PMID 40076620, 2025).
Fanconi anemia (1 paper, 2019). Fanconi anemia (FA) is a hereditary DNA repair disorder characterized by progressive pancytopenia with bone marrow failure, variable congenital malformations and predisposition to develop hematological or solid tumors. "Indeed, this NEK2 inhibition is dependent of ATM, a protein that, along with ATR, are master controllers of cell cycle and DNA repair, the main pathway deregulated in Fanconi Anemia." (PMID 31266445, 2019).
head and neck carcinoma (1 paper, 2019). A carcinoma that arises from the head and neck region. "Because we reported that NEK2 was highly expressed in the head and neck carcinoma, we further compared two public GEP datasets for NPC and normal nasopharyngeal epithelia control (NC) including 41 (10 NC and 31 NPC) and 28 (3 NC and 25 NPC) cases, respectively." (PMID 30295336, 2019).
hepatitis B (1 paper, 2021). "Among them, PTTG1, MAD2L1, CDK1, and NEK2 may be the key prognostic genes of the hepatitis B inflammation and cancer transformation." (PMID 34539726, 2021).
invasive breast carcinoma (1 paper, 2021). A carcinoma that infiltrates the breast parenchyma. "On the other hand, in MDA-MB-231 invasive breast cancer cells silencing or chemical inhibition of Nek2 had the opposite effect of increasing E-cadherin protein expression." (PMID 33907253, 2021).
leiomyosarcoma (1 paper, 2025). An uncommon, aggressive malignant smooth muscle neoplasm, usually occurring in post-menopausal women. "The overexpressed kinases in osteosarcoma, liposarcoma, and leiomyosarcoma are mainly serine/threonine kinases (BUB1, CKD4, HUNK, LKKK1, NEK2, PBK, PLK1, and PLK4), whereas TTK has a dual role (Tyrosine and serine/threonine kinase) and only MELK presents tyrosine phosphorylation activity." (PMID 40723917, 2025).
liver cirrhosis (1 paper, 2017). "Notably, through literature reviews, we found that CLDN10, CDKN3, CRHBP and NEK2 were reported to be associated with HCC, and SPINK1 was associated with liver cirrhosis." (PMID 28036264, 2017).
lung NET (1 paper, 2020). "Unfortunately, it was not possible to perform a statistical analysis evaluating the prognostic value of PIM and NEK2 expression in lung NET patients due to no deaths and a small number of relapses in this group." (PMID 32504181, 2020).
medullary thyroid carcinoma (1 paper, 2020). "In the broad spectrum TMA analysis (semiquantitative and quantitative), we observed an increased expression of NEK1, NEK2, NEK3, and NEK5 in papillary and medullary thyroid carcinoma." (PMID 31906878, 2020).
medulloblastoma (1 paper, 2020). A malignant, invasive embryonal neoplasm arising from the cerebellum. "The testing of the NEK2 as a top candidate showed a strong dependency of medulloblastoma cells on the activity of this enzyme." (PMID 33101383, 2020). "Studies showed that NEK2, OTX2 target gene, was knockdown and pharmacological inhibition decreased medulloblastoma cell viability." (PMID 33101383, 2020).
ovarian endometriosis (1 paper, 2024). A non-neoplastic disorder characterized by the growth of endometrial tissue in the ovaries. "In conclusion, our experimental data show that NEK2 is increased in both ectopic and eutopic endometrium from women with ovarian endometriosis." (PMID 38795132, 2024).
pancreatic neuroendocrine tumor (1 paper, 2020). Pancreatic endocrine tumor, also known as pancreatic neuroendocrine tumor (PNET), describes a group of endocrine tumors originating in the pancreas that are usually indolent and benign, but may have the potential to be malignant. "NEK2 gene expression was also positively associated with high tumor grade of pancreatic neuroendocrine tumors." (PMID 32504181, 2020). "Accumulating evidence have shown that mRNA and/or protein level of NEK2 is upregulated in primary tumor tissues or cancer cell lines of several cancers, i.e., in pancreatic neuroendocrine tumors." (PMID 32504181, 2020).
papillary renal cell carcinoma (1 paper, 2020). A rare subtype of renal cell carcinoma, arising from the renal tubular epithelium and showing a papillary growth pattern, which typically manifests with hematuria, flank pain, palpable abdominal mass or nonspecific symptoms, such as fatigue, weight loss or fever. "The over-expression of NEK2 was observed in 4 of the 6 highly malignant papillary renal cell carcinomas with chromosome 1q duplication." (PMID 31906878, 2020).
pituitary adenomas (1 paper, 2021). "The expression of NEK2 was examined using quantitative real-time PCR, western immunoblotting, and immunohistochemistry - both in pituitary adenomas (PA) and in normal pituitary tissue." (PMID 33754007, 2021).
rectal cancer (1 paper, 2026). A primary or metastatic malignant neoplasm that affects the rectum. "The combination of NEK2 small interfering RNA and cisplatin has been shown to inhibit the growth of rectal cancer cells." (PMID 41358726, 2026).
Sepsis (1 paper, 2024). Sepsis is defined as life-threatening organ dysfunction caused by a dysregulated host response to infection. "Mice subjected to cecal and ligation-puncture-induced sepsis presented with elevated NEK2 expression levels in their lungs, and studies on experimental cancers suggest that this kinase is involved in cancer progression and drug resistance." (PMID 38895505, 2024).
thyroid (1 paper, 2020). "Here, we studied the expression of NEK1, NEK2, NEK3, and NEK5 in different types of normal and malignant tissues, using tissue microarray analysis, and identified NEKs as potential markers in thyroid malignancy." (PMID 31906878, 2020). "Once NEK1, NEK2, NEK3, and NEK5, all showed a higher level of expression in thyroid tumour tissue it was decided to expand the number of thyroid cases submitted to TMA analysis." (PMID 31906878, 2020).
uveal melanoma (1 paper, 2024). A melanoma derived from melanocytes of the uveal tract. "Inhibition of NEK2 culminated in apoptotic cell death, indicating that NEK2 is required for survival of uveal melanoma cells." (PMID 38182898, 2024). "We also identified NIMA-related kinase (NEK2) as a candidate target downstream of YAP contributing to the transformation of YAP-dependent uveal melanoma cells." (PMID 38182898, 2024).